MET (MET proto-oncogene, receptor tyrosine kinase)
Diseases named in the same sentence as MET in open-access papers (continued):
Sharing a sentence is not in itself a finding about the gene and the disease.
cancer (continued). "ABN401 was cytotoxic against several MET-addicted cancer cell lines and inhibited c-MET phosphorylation, as well as downstream signaling." (PMID 32549194, 2020). "Hepatocyte growth factor (HGF) known as a multifunctional growth factor that upregulates cancer cell motility, invasiveness, proliferative, and anti-apoptotic activities through phosphorylation of MET (a specific receptor of HGF)." (PMID 32290402, 2020). "Michieli and colleagues showed that the transforming potential displayed by mutant forms of MET found in human cancer is sensitive to, and can be entirely dependent on, the availability of the ligand HGF." (PMID 33271944, 2020). "HGF and its physiological receptor tyrosine kinase MET have been reported to be involved in acquired resistance to various tyrosine kinase inhibitors and have been proposed as critical targets in cancer therapy." (PMID 32245422, 2020). "Thus, a longitudinal study of immune gene expression in MET-mutated cancers could be performed in the future to better inform the potential of immune-targeting therapies in this population; however, access to longitudinal samples from solid tumors for research purposes is limited." (PMID 33437521, 2020). "The regulatory role of HAI-2 in the activation of pro-HGF by inhibiting the activating proteases (including matriptase), which induces HGF/MET signaling axis, has been considered a major suppressive function in cancer progression." (PMID 32290402, 2020). "Without expression of these proteoglycans, there is decreased regulation of several established and potent oncogenic pathways such as EGFR, TGFβ, MYC, and c-MET that can lead to cancer growth and metastasis." (PMID 32553107, 2020). "Though HGF/c-MET signalling plays an important role in embryonic development and wound healing, this pathway is rarely active in adults apart from malignancies." (PMID 33271944, 2020). "In fact, the importance of the MET signaling pathway in relation to cancer cell survival following PDT remains largely unexplored." (PMID 32485915, 2020). "In the course of cancer therapy, MET and EGFR signaling pathways are often targeted either by monoclonal antibodies to prevent binding of activating ligands or by small-molecule inhibitors of receptor phosphorylation." (PMID 32316583, 2020). "Here, the authors show that in head and neck and lung squamous carcinoma, a polymorphic MET variant enhances binding to HER2, resulting in activation of HER2 signalling and progression of the cancers." (PMID 32214092, 2020). "Activation of HGF/MET signaling axis in cancer cells also plays a significant role in proliferation, angiogenesis, epithelial-mesenchymal transition (EMT), and drug resistance." (PMID 32290402, 2020). "ABN401 was highly selective for MET among 571 kinases (369 wildtype kinases and 202 kinase mutants) and showed >90% cytotoxicity in MET-addicted cancer cells." (PMID 32549194, 2020). "Potency and efficacy of TR1801‐ADC in 15 cancer cell line with various cMet expression levels and MET amplification status." (PMID 31736230, 2020). "Abnormal c-MET signaling has been demonstrated in a number of human cancers as a result of c-MET receptor overexpression, receptor mutation or amplification, HGF overexpression or the formation of abnormal autocrine signaling." (PMID 32117721, 2020). "Initially identified in a screen for oncogenes, MET is overexpressed in numerous cancers (reviewed in Ref." (PMID 33087447, 2020). "The hepatocyte growth factor (HGF)/c-MET pathway is upregulated in PC and mediates the interaction between cancer cells and stromal pancreatic stellate cells (PSCs)." (PMID 32203220, 2020). "The HGF/c-MET pathway that mediates cross-talk between pancreatic stellate cells (the main collagen producing stromal cells) and cancer cells, as well as between PSCs and endothelial cells, is a potentially useful target for therapy." (PMID 33271944, 2020).
cancer (continued). "MET inhibitors show great promise for cancer treatment where there is MET amplification/over-expression and activation." (PMID 33149187, 2020). "In NSCLC, MET pathway activation is thought to occur through a diverse set of mechanisms that influence properties affecting cancer cell survival, growth, and invasiveness." (PMID 32549766, 2020). "Aberrant activation of MET signaling does not only affect cancer development and progression, but it also contributes to resistance against other cancer drugs." (PMID 32093126, 2020). "Our findings clearly indicate that it is the triple therapy (the combination of a chemotherapeutic agent with compounds that inhibit both arms of HGF/c-MET pathway) that gives the best outcomes in terms of preventing cancer progression." (PMID 32203220, 2020). "Gemcitabine alone or in dual or triple combinations with HGF/c-MET inhibition significantly reduced proliferating cancer cells compared with the rest of treatments." (PMID 32203220, 2020). "Crizotinib is a first-line chemical approved for the treatment of NSCLC and other cancers with ALK and ROS1 mutations or c-MET amplification 2-5." (PMID 32792859, 2020). "Surprisingly, and in contrast to the lack of effect on metastasis in vivo, we found that inhibition of both HGF and c-MET (over a period of 4 weeks in culture) significantly decreased the invasion of cancer cells into the collagen matrices." (PMID 32203220, 2020). "As many novel anti-cancer therapies target immunoregulatory molecules or the c-MET receptor itself understanding the relationship between c-MET and immunological responses to tumors is critical in ensuring these drugs are used to their full potential benefit." (PMID 32117721, 2020). "Once HGF binds to c-MET on cancer cells, uPA production by cancer cells is induced, leading to activation of more pro-HGF to active HGF." (PMID 33271944, 2020). "c-MET is required for the egress of neutrophils from the bone marrow and transendothelial migration of neutrophils into tissues in murine models of cancer." (PMID 32117721, 2020). "Since the HGF/MET axis plays an important role in cancer, various approaches have been explored to inhibit it, including the use of MET-neutralizing antibodies, HGF antagonists, and tyrosine kinase activity-targeted inhibitors (TKIs)." (PMID 32435640, 2020). "Here, we investigated the levels of PDL1 and MET expression in isolated CTCs because they are two of the most promising therapeutic targets in cancer." (PMID 32486306, 2020). "SPINT2 gene expression was down-regulated, altering dysregulation of the HGF/MET signaling pathway, which contributes to cancer development and progression." (PMID 32256213, 2020). "Cancer-associated fibroblasts also reprogram the ECM to retain more paracrine HGF, which in turn positively affects the activation of c-MET and its downstream signaling pathways, thereby causing further resistance to MET inhibitors." (PMID 33271944, 2020). "(-)-Oleocanthal (OC) is a naturally occurring phenolic secoiridoid exclusively occurring in EVOO and showed documented anti-breast and other cancer activities via targeting c-MET." (PMID 32545325, 2020). "The results of this study clearly identified MET signaling as an additional auto- and paracrine survival pathway in cancer cells that can be induced and sustained by HGF secretion from perishing stromal cells." (PMID 32485915, 2020). "In cancer, c-MET activation promotes communication between mesenchymal cells and epithelial cells, tissue infiltration, cancer cell proliferation, and the induction of angiogenesis." (PMID 33396187, 2020). "The main reason why previous clinical trials did not achieve their efficacy endpoints is the lack of the appropriate selection of cancer patients in which the cancer growth depends on the activation of MET (pMET)." (PMID 33121208, 2020).
cancer (continued). "Based on current progress, this review summarizes the current challenges and simultaneously proposes future opportunities for HGF/MET targeting for therapeutic cancer interventions." (PMID 32435640, 2020). "Increased expression of MET with worse prognosis has been reported in various cancer cells, and phosphorylation (activation) potently promotes invasion and metastasis." (PMID 32290402, 2020). "Several studies have investigated the role of c‐MET or PARP‐1 inhibition as putative targets for cancer therapy." (PMID 32686903, 2020). "Here, the efficacy of ABN401, a MET inhibitor, was investigated using histopathologic and genetic analyses in MET-addicted cancer cell lines and xenograft models." (PMID 32549194, 2020). "Previous reports suggest that ERBB1/2 and c-MET pathways play an important role in metastatic progression of different cancers, including BC." (PMID 33019652, 2020). "The signaling of the HGF/SF/MET system plays a crucial role in the regeneration of several tissues such as the liver or the skin, while its deregulation is often observed in cancer." (PMID 32444769, 2020). "c-MET activation in cancer promotes; communication between mesenchymal cells and epithelial cells, tissue infiltration, cancer cell proliferation, and the induction of angiogenesis." (PMID 32117721, 2020). "ABN401 is a potent and highly selective MET inhibitor in MET-addicted cancers and shows a favorable PK profile." (PMID 32549194, 2020). "Our panel included cancer cell lines with activating PIK3CA mutations, inactivating PTEN mutations, AKT gene amplification or amplification of either ERBB2 or MET (both of which have been previously shown to be associated with AKT dependence)." (PMID 32439931, 2020). "In cancer cells overexpressing hepatocyte growth factor receptor (HGFR/MET), heterogeneity occurred as a molecular mechanism of drug resistance after chemotherapy." (PMID 31936346, 2020). "In this work, we used single-molecule super-resolution microscopy to visualize single receptor clusters of EGFR and MET in two cancer cell lines." (PMID 32316583, 2020). "We have demonstrated that phosphorylation of multiple RTKs, such as EGFR, FGFR2, IGF1R, and MET, can be regulated by O-glycosylation in various cancers." (PMID 32005975, 2020). "The prevalence of c-MET positive T-cells in other cancers, their functional capacities and the consequences of c-MET inhibition on T-cell function requires ongoing research." (PMID 32117721, 2020). "Known resistance factors to EGFR-targeted therapies in other cancer types include mutations and overexpression of the receptor tyrosine kinases AXL or MET." (PMID 32119655, 2020). "Signal transduction pathways other than TLR4 and c-MET also have cancer promoting activities to a substantial extent." (PMID 33217986, 2020). "Another monoclonal antibody (mAb), ornartuzumab, targeting the hepatocyte growth factor receptor/tyrosine-protein kinase Met (HGFR/c-MET) receptor’s extracellular domain was reported to prevent the cancer growth in orthotopic U87 GBM xenograft." (PMID 33321953, 2020). "MET aberrant cancers have considerable potential for targeted therapy, and c-MET is a promising clinical target that has been investigated in many clinical trials." (PMID 32549194, 2020). "The results showed that the upregulated mrDEGs were enriched in several cancer-related pathways, such as MET activates PTK2 signaling, PI3K signaling, negative regulation of binding, and positive regulation of Wnt signaling pathway." (PMID 31959204, 2020). "MET-amplified cancers have c-MET overexpression, which is a sensitive indicator of the efficacy of MET inhibitors." (PMID 32549194, 2020). "The favourable effects of MET activation, resulting from the administration of our agonist mAb, encourage its use in lowering the adverse effects of anthracyclines in cancer therapy." (PMID 32133617, 2020).
cancer (continued). "Overactivation (induced by increased HGF-activating TTSPs or decreased HAIs) revealed cancer progression through MET phosphorylation." (PMID 32290402, 2020). "MET activation can be driven in cancer by several mechanisms: HGF or MET overexpression, and also mutations." (PMID 32093126, 2020). "In particular, the EGR receptor (EGFR) and HGF receptor c-MET are highly expressed in many carcinomas." (PMID 32679742, 2020). "These experiments demonstrate that pre-treatment of anti-MET antibodies can effectively block the subsequent HGF-mediated AXL co-activation in these cancer cells, and such effects can be detected within less an hour following a 7-minute antibody exposure." (PMID 30760737, 2019). "Dual inhibition of EGFR and MET has previously been demonstrated to suppress invasion of cancer cells." (PMID 31506424, 2019). "Using Western Blot, we also noticed increased levels of EGFR, MET, and selected markers of cancer stem cells in generated cell lines." (PMID 31877948, 2019). "c-MET pathway over-activation is the signature of malignancy acquisition or chemotherapy resistance of many cancers." (PMID 30646583, 2019). "The high sensitivity of cancer cells with MET amplification defines their “MET addiction”, which is related to the constitutive activation of this receptor, because of its ligand-independent dimerization when overexpressed at the cell surface." (PMID 31040922, 2019). "Again, with both cell lines, we have observed that the biotin-conjugated anti-MET antibodies can effectively block HGF-induced cancer cell invasion." (PMID 30760737, 2019). "In cancer, HGF binding to MET can be paracrine or autocrine, as HGF produced by stromal fibroblasts can bind to MET on neighboring cancer cells, or cancer cells can produce both HGF and MET." (PMID 30631034, 2019). "Through MET amplification, the poorly differentiated early cancer progressed to advance cancer and metastasis." (PMID 31842404, 2019). "The HGF/c-MET axis especially affects the migration of cancer cells from the primary site to other organs by promoting epithelial-mesenchymal transition (EMT), which initiates cancer cell metastasis." (PMID 31355133, 2019). "For example, the combination of a TRK and MET inhibitor achieved a confirmed response to therapy in a patient with a TRK fusion-positive cancer with MET amplification-driven resistance to a first-generation TRK inhibitor." (PMID 31738426, 2019). "Capmatinib, an inhibitor of the tyrosine-protein kinase MET (c-MET), was first developed to treat cancer patients with alterations affecting the c-MET pathway in cancer cells due to activating mutations, overexpression, gene amplification, and translocations." (PMID 31616408, 2019). "The proto-oncoprotein MET is a receptor tyrosine kinase that plays a key role in cancer cell growth and invasion." (PMID 30760737, 2019). "Since the MET receptor plays a key role in cell migration and invasive growth of various cancer cells, we examined the potential effects of anti-MET antibodies on cell migration." (PMID 30760737, 2019). "Since the high level expression of MET is correlated with poor prognosis of various cancers, MET serves as an excellent target for cancer therapy." (PMID 30760737, 2019). "Combination of CET with FGFRi had minimal impact on pERK and cancer cell growth, whereas combination with a MET inhibitor (METi) showed a clear reduction of both." (PMID 31287991, 2019). "Studies from the past decade have shown that RON and MET play a role in most known cancer subtypes and are potential markers of poor prognosis and therapeutic target in a number of cancers." (PMID 31867280, 2019). "Increasing evidence demonstrates that abnormal activation of HGF/c-MET was involved in the cancer progression." (PMID 31426831, 2019). "Our data indicate that these anti-MET antibodies are biologically inhibitory to the MET signaling pathway for cancer cell invasion." (PMID 30760737, 2019).
cancer (continued). "MET, also known as hepatocyte growth factor (HGF) receptor, is a receptor tyrosine kinase that promotes tissue growth in developmental, wound-healing, and cancer metastasis." (PMID 31652258, 2019). "Such uptake can also be demonstrated directly by EV-mediated transfer of cancer-related signalling receptors (e.g. MET), or RNA from cancer cells to myeloid cells in vivo." (PMID 32038264, 2019). "MET is a receptor tyrosine kinase that plays an important role in cancer development and progression." (PMID 31480591, 2019). "There is aberrant RON and MET expression and activation in various cancers, including gastric, prostate, ovarian, and breast cancer, and such aberrations contribute to cancer cell proliferation, invasiveness and metastasis." (PMID 31867280, 2019). "HGF binds to the HGF receptor c-MET, inducing several biological activities involved in cancer progression." (PMID 31355133, 2019). "It was recently reported that the MET pathway is involved in PD-L1 up-regulation in cancer cells, but its role in the down-regulation of co-stimulatory molecules was not addressed." (PMID 31480591, 2019). "For example, MET and EGFR are well-known to cause mutual cross-resistance to targeted therapy in different cancer types." (PMID 30881919, 2019). "Our work indicates that MET inhibition significantly enhances therapeutic inhibition of growth by CDK4/6is in preclinical models of human cancer." (PMID 31296956, 2019). "Gene fusion resulting in kinases activation is a common relevant mechanism in cancer malignancy and many known fusions implicating MET were described in different types of cancers." (PMID 31040922, 2019). "Taken together, these data suggest that paroxetine suppresses cancer progression via the inhibition of the common RTK pathway involving MET‐p38, and JNK in both the cell lines." (PMID 30421568, 2019). "Herein, we present a characterization of the established cell lines and their resistance mechanisms, which comprise the overexpression and hyperactivation of EGFR and MET, the emergence of cancer stem-like cell traits, and elevated invasive abilities." (PMID 31877948, 2019). "Since functional cross-talk of MET was described in various cancers with other RTKs, we also analyzed the eventual cross-talk of MET with EGFR which is known to be significantly expressed in the TTA1 cell line." (PMID 31040922, 2019). "The potential role of MET in PD-L1 overexpression in human cancers was further examined by IHC of the NSCLC tissues from patients as well as by referencing the Cancer Cell Line Encyclopedia (CCLE) for pan-cancer cell lines and the TCGA for pan-cancers." (PMID 31480591, 2019). "The HGF/c-MET axis has recently become a therapeutic target for the treatment of various types of cancer." (PMID 31355133, 2019). "We have recently found that in various cancer cells, MET can be induced to form clusters on the plasma membrane in response to its natural ligand HGF stimulation." (PMID 30760737, 2019). "The protein tyrosine kinase MET also complexes with β-catenin to integrate multiple downstream signals contributing to the development and progression of cancer." (PMID 31085796, 2019). "The HGF-activated c-MET signalling pathway has been extensively studied, especially for its relationship with cancer progression." (PMID 30646583, 2019). "Treatment of these cancer cells with the bivalent anti-MET antibodies induces only a transient activation of MET RTK activities." (PMID 30760737, 2019). "Lactate can act as a signaling molecule which instructs cancer associated fibroblasts (CAFs) to produce hepatocyte growth factor (HGF), whose secretion activates MET signaling in cancer cells, overcoming TKI inhibitory effects." (PMID 31795465, 2019). "How to effectively target the over-expressed or abnormally activated MET proteins is an important question for developing novel anti-cancer therapeutics." (PMID 30760737, 2019).